INS (insulin)
Diseases named in the same sentence as INS in open-access papers (continued):
Sharing a sentence is not in itself a finding about the gene and the disease.
Insulin resistance (continued). "The reduction of weight gain and improvement of metabolic parameters, such as total cholesterol, low-density lipoprotein-cholesterol, glucose and insulin tolerance, fasting glucose levels, and hepatic insulin resistance has been seen in rats, mice, and hamsters." (PMID 28587078, 2017). "Within IGR groups, dyslipidemia might diminish the compensatory insulin secretion to insulin resistance in subjects with CGI." (PMID 28199386, 2017). "Treatment with both metformin and metformin + HCE significantly reduced the fasting blood glucose and serum insulin levels as well as Homeostatic Model Assessment for Insulin Resistance (HOMA-IR), baseline corrected ipITT glucose area under the curve (AUC), and baseline corrected OGTT glucose AUC." (PMID 28937612, 2017). "In relation to glucose metabolism, although it was shown that irisin is able to ameliorate general glucose metabolism, we did not observe any change on insulin sensitivity when performing an insulin resistance experiment (High glucose/high insulin) with FNDC5-KO adipocytes." (PMID 29176631, 2017). "The positive correlation between Phe and/or Tyr and insulin secretion may be involved in pathways to compensate early stage of insulin resistance through stimulating insulin secretion." (PMID 28287627, 2017). "Considering the importance of skeletal muscle in the regulation of glucose control and insulin resistance, alantolactone may be a potent candidate for the treatment of glucose intolerance and insulin resistant treatment in the future." (PMID 28706484, 2017). "Nonetheless, these hypotheses converge in the findings that deregulated insulin signaling or insulin resistance in the brain activates Glycogen Synthase Kinase 3 (GSK3), which enhances Aβ production and Tau phosphorylation." (PMID 28282917, 2017). "As betatrophin action could reflect a compensatory response in insulin resistant state and is proposed as a marker of insulin resistance, it is important to take these indices into consideration while comparing the results of different studies." (PMID 28702052, 2017). "Fasting plasma glucose, insulin, insulin resistance, glycated haemoglobin, and Human Placenta Lactogen were significantly increased (p<0.0001) in the pregestational diabetic controls, whereas, progesterone and estradiol were significantly increased in the nondiabetic pregnant women." (PMID 28732072, 2017). "Already young adult individuals born with low birth weight show signs of metabolic impairment related to insulin resistance including an altered fat distribution, increased lipolysis, and reduced expression of key insulin signaling proteins in insulin target tissues." (PMID 29026446, 2017). "We then determined whether or not the application of Heqi San could change the homeostasis model assessment-insulin resistance index (HOMA-IR) or the insulin sensitivity index (ISI) in the PCOS model." (PMID 29020999, 2017). "There are strong associations between skeletal muscle lipid accumulation and insulin resistance in both humans and animals, but the precise lipid species that are involved in impairing muscle insulin action are not fully resolved." (PMID 29066734, 2017). "The brain insulin resistance may be due to peripheral insulin resistance, reduced insulin uptake by brain and elevated brain Aβ deposition." (PMID 28505155, 2017). "To further address whether UC-MSCs reveal therapeutic abilities to attenuate insulin resistance in vitro, we measured the inflammatory factor production and insulin signaling transduction in liver, adipose, and skeletal muscle tissues." (PMID 29096724, 2017). "For example, dyslipidemia (i.e., increased triglycerides, reduced high density lipoprotein cholesterol), which is a key predictor in cardiovascular mortality with cigarette smoking, is significantly worse in smokers with insulin resistance compared with more insulin-sensitive smokers." (PMID 28304347, 2017).
Insulin resistance (continued). "As summarized in this review, our laboratory has demonstrated in the last couple of decades that loss in hepatic CEACAM1 expression and its defective phosphorylation impair insulin clearance and subsequently, play a pivotal role in insulin resistance, fatty liver disease, and obesity." (PMID 28184213, 2017). "As obesity is closely related to insulin resistance and increased sympathetic nerve activation, piceatannol may exert beneficial effects on insulin sensitivity, BP and HR in overweight men." (PMID 29057795, 2017). "Insulin sensitivity test demonstrates insulin resistance in both female and male Wt mice fed HCFD." (PMID 28797077, 2017). "Moreover, SIRT1 activation protects from insulin resistance and helps with glucose homeostasis in different insulin sensitive organs." (PMID 27659520, 2017). "Therefore, the aim of this study is to investigate the relationship between AGEs and insulin secretion and insulin resistance in the type 2 DM subjects by using LC-MS/MS methods." (PMID 28695132, 2017). "Since Albumin synthesis is sensitive to insulin, they speculated that reduced serum albumin concentrations and biosynthesis is a result of high fat diet- induced insulin resistance." (PMID 28482801, 2017). "A possible explanation is that longtime and severe insulin resistance could result in the decrease of insulin secretion, which may alleviate further deterioration of insulin resistance." (PMID 28199386, 2017). "Finally, the HOMA-IR and serum fasting insulin level were used as insulin resistance indices in the current study, but the gold standard test to determine insulin resistance is the hyperinsulinemic-euglycemic clamp study." (PMID 28704413, 2017). "It has been speculated that peripheral insulin clearance is reduced because of cirrhosis, and then insulin resistance and glucose abnormalities occur secondary to hyperinsulinemia." (PMID 28505202, 2017). "Compared to controls, ob/ob mice in the NAFLD group had significant elevations in energy intake, body weight, lipids, glucose, insulin, the homeostasis model assessment of insulin resistance (HOMA-IR), alanine aminotransferase (ALT), and aspartate aminotransferase (AST)." (PMID 29312569, 2017). "As a result of these processes, the foetus may be adapted to adverse nutritional conditions by reducing ability to produce insulin and by occurrence of insulin resistance." (PMID 28273874, 2017). "Finally, insulin resistance was also attributed to a decreased insulin-stimulated whole body glucose disposal, which was notably due to decreased glucose uptake in brown adipose tissue and the heart." (PMID 28534852, 2017). "Studies have reported that insulin resistance with compensating hyperinsulinemia may be related to increased bone mass because insulin exerts an anabolic effect on bone formation." (PMID 28704413, 2017). "Interestingly, overexpression and inhibition of ATF4 in the hypothalamus induces hepatic insulin resistance and improves hepatic insulin sensitivity, respectively." (PMID 28555094, 2017). "Given the effects of BCAA catabolism on insulin sensitivity, what role might BCAAs play in reversing insulin resistance?" (PMID 28991180, 2017). "Furthermore, GK rats had insulin resistance, impaired pancreatic β-cells function, decreased β-cells volume, and reduced insulin secretion since they were at the age of 2 months old, leading to hypoinsulinemia with hyperglycemia in their advanced age." (PMID 28923829, 2017). "In addition to improving pancreatic insulin secretion, experimental models show that osteocalcin can protect against high-fat-induced obesity, insulin resistance, and nonalcoholic fatty liver disease (NAFLD)." (PMID 28194185, 2017). "The antinatriuretic effect of insulin may contribute to the relationship between insulin resistance and hypertension, and patients in the low UNa tertile also require less antihypertensive therapy." (PMID 28255559, 2017).
Insulin resistance (continued). "Impairment of GLUT4 expression, GLUT4 translocation and/or insulin signaling may affect insulin-stimulated glucose uptake and will result in insulin resistance and hyperglycemia." (PMID 29099085, 2017). "Therefore, it is important to screen obese children for insulin resistance using either fasting insulin or HOMA-IR." (PMID 28754153, 2017). "Polysaccharides extracted from Pleurotus eryngii (belonging to Pleurotaceae) down-regulated fasting serum glucose and insulin concentrations by enhancing antioxidant activity in the liver of mice fed with fructose diet, with an amelioration of hepatic insulin resistance." (PMID 28146130, 2017). "Taken together, relatively elevated fasting insulin levels might point towards a higher gluconeogenic activity, or also towards early stages of insulin resistance or fatty liver." (PMID 28817652, 2017). "Therefore, the use of insulin or HOMA-IR as a screening tool for early detection of insulin resistance is highlighted by this study." (PMID 28754153, 2017). "This association may be mainly based on the effect of hyperinsulinemia, insulin resistance and cancer pathogenesis on the insulin/ insulin-like growth factor (IGF) system, which plays a critical role in the pathogenesis, progression, and prognosis of CRC." (PMID 28423026, 2017). "Moreover, variety of cell types has been reported to develop insulin resistance following the long-term insulin treatment." (PMID 28236091, 2017). "Several studies have reported that insulin resistance would not be significantly involved in the causes of T2DM in PWS due to the better insulin sensitivity of patients compared to obese individuals with PWS." (PMID 28854950, 2017). "Such experiments have raised doubts whether insulin resistance and inadequate insulin production is necessary and sufficient for hyperglycemia in T2DM." (PMID 28767672, 2017). "n-3 PUFAs have anti-inflammatory and insulin-sensitising effects that could make them a useful treatment to prevent the long-term effects of maternal insulin resistance in the offspring." (PMID 28717143, 2017). "However, treatment with metformin, WE, 50% ME, and ME of P. niruri markedly reduced FFAs by 26.2%, 15.9%, 25.3%, and 32.5%, respectively, restored insulin levels to normal, and ameliorated insulin resistance." (PMID 28718838, 2017). "By examining the effects of celastrol on glucose tolerance and insulin insensitivity, we found that celastrol could ameliorate obesity-disrupted glucose homeostasis and insulin resistance." (PMID 29040966, 2017). "Furthermore, we evaluated the changes in glucose tolerance, insulin secretory response, and tissue-specific insulin resistance in these pigs after the dietary intervention." (PMID 29046729, 2017). "Indeed, we observed aggravated apoptosis in Stk25 transgenic pancreas, which probably contributed to the lost ability to increase insulin secretion in the context of insulin resistance." (PMID 28442507, 2017). "Studies have shown that IKK can not only activate NF-κB by phosphorylating IκB, but also lead to the phosphorylation of IRS-serine 307, which inhibits normal tyrosine phosphorylation, and interferes with the insulin signaling pathway, ultimately leads to insulin resistance." (PMID 29240812, 2017). "Astragaloside II (M94, OB = 0.79%, and DL = 0.13) and isoastragaloside I (M104, OB = 37.80%, and DL = 0.14) could alleviate insulin resistance and glucose intolerance by enhancing the expression of an insulin-sensitizing adiponectin." (PMID 29051733, 2017). "Particularly, the observed effect of TGS to reduce blood glucose and insulin in the immediate postprandial phase as well as its effect on phospholipid metabolism may be favorable for moderating insulin resistance." (PMID 28300770, 2017). "For example, insulin resistance may directly affect bone mass because bone is a metabolically active organ and a target organ of insulin." (PMID 28704413, 2017).
Insulin resistance (continued). "Besides decreasing insulin resistance and improving hepatic insulin sensitivity, sitagliptin seems also to prevent steatosis through GLP-1R signalling in the liver and reduction of endoplasmic reticulum stress." (PMID 29098166, 2017). "Fourth, the shortage of records using of medications, insulin and insulin resistance in this study may have an effect on proteinuria, which therefore warrants further analysis." (PMID 28807011, 2017). "IR in PCOS women was measured by indirect methods, including fasting blood sugar (FBS), fasting insulin (FI), glucose/insulin, homeostatic model assessment of insulin resistance (HOMA-IR), quantitative insulin sensitivity check index (QUICKI), and MacAuley index." (PMID 29177243, 2017). "By suppressing the activation of NF-κB by inhibiting NF-κB alpha (IκBα) degradation and phosphorylation of JNK/p38 mitogen-activated protein kinases (JNK/p38 MAPKs), M. charantia can inhibit inflammation and improve the insulin signaling pathway, thereby ameliorating insulin resistance." (PMID 29164155, 2017). "In some recent studies, vitamin D supplementation have been identified as a risk modifier for T2DM, as it improves insulin secretion and reduces insulin resistance in T2DM and non-diabetic subjects." (PMID 28423063, 2017). "Blocking IL-22 signaling resulted in unfavourable effects on body weight, glucose tolerance and insulin sensitivity, whereas treatment with recombinant IL-22 proteins or IL-22 overexpression counteracted weight increase and improved hyperglycaemia, insulin resistance and inflammation." (PMID 28143481, 2017). "Therefore, the aim of the present study was to investigate serum betatrophin concentrations after glucose load and its relationship with indirect indices of insulin resistance and insulin secretion in women with PCOS in comparison to the healthy controls." (PMID 28702052, 2017). "Saturated fatty acids are known to effect insulin secretion and insulin resistance, and although there is mounting evidence suggesting that insulin resistance is involved in the carcinogenesis of the pancreas, the mechanisms in which dietary fats effect insulin action is unclear." (PMID 28294968, 2017). "HFD feeding was likely to induce insulin resistance and increase the circulating insulin level." (PMID 28935866, 2017). "Furthermore, the relationship between serum insulin levels and insulin resistance with CNV was assessed in INS." (PMID 28428959, 2017). "Since some researchers have argued for compensatory insulin resistance in response to primary hyperinsulinemia, we reversed the causal arrow between insulin resistance and insulin levels which again did not affect bi-stability." (PMID 28767672, 2017). "Activating Nrf2 could intermittently decrease ROS production, enhance insulin sensitivity, and improve insulin resistance." (PMID 28708100, 2017). "At this stage of insulin resistance, reduction of insulin sensitivity could still be adequate to keep fasting blood glucose in normal range, but when challenged with a meal or a glucose upload, postprandial glucose tolerance becomes abnormal." (PMID 27814245, 2017). "Finally, GLP-1 can alleviate insulin resistance in the AD brain, suggesting that impaired glucose metabolism and insulin resistance leads to severe memory dysfunction." (PMID 29165354, 2017). "The main pathways in the KEGG enrichment analysis were ‘Insulin resistance’ (P = 0.00628), ‘Phenylpropanoid biosynthesis’ (P = 0.043731), ‘Thyroid hormone synthesis’ (P = 0.008421), ‘Insulin signaling pathway’ (P = 0.003445) and ‘Starch and sucrose metabolism’ (P = 0.017741)." (PMID 28720800, 2017). "Four studies also recorded fasting blood glucose (FBG), two studies recorded serum glucose, one study recorded serum insulin and homeostasis model assessment-estimated insulin resistance (HOMA-IR); one study recorded administered insulin dose; and one study recorded BMI and C-peptide levels." (PMID 28467470, 2017).
Insulin resistance (continued). "Elevated hepatic glucose production, impaired insulin secretion, and insulin resistance - abnormalities of glucose metabolism typically found in subjects with obesity - are major factors underlying the pathogenesis of type 2 diabetes (DM2) and the metabolic syndrome (MS)." (PMID 29412387, 2017). "T2D is characterized by insulin resistance and/or impaired insulin secretion from beta cells." (PMID 28287627, 2017). "In our studies of healthy volunteers, hydrocortisone infusion resulted in a substantialplasma cortisol increase, with abolition of the diurnal cortisol variation.Hypercortisolemia is known to induce insulin resistance by affecting postreceptor insulin signaling and decreasing glucoseclearance." (PMID 28323916, 2017). "High insulin in insulin resistance may inhibit the ability of interferon alfa to block HCV replication due to the activation of PI3K by insulin, thus leading to inhibition of STAT-1, which is involved in the interferon alfa pathway." (PMID 28981513, 2017). "Indeed, obesity induced S-nitrosation of hypothalamic IR and Akt, whereas inhibition of iNOS or S-nitrosation of insulin signaling pathway protected against hypothalamic insulin resistance and normalized energy homeostasis." (PMID 28835706, 2017). "As insulin resistance in CKD is associated with diabetes, kidney disease could also lead to a deterioration of insulin sensitivity." (PMID 28459862, 2017). "People with insulin resistance need more insulin to help glucose enter the cells." (PMID 28469250, 2017). "Also, HFD rats had a blunted response to insulin, indicative of insulin resistance as assessed by intraperitoneal insulin tolerance test (IpITT)." (PMID 28628674, 2017). "This provides a potential molecular mechanism that underlies defective- or non-response to insulin in AT patients, leading to the development of insulin resistance and T2DM." (PMID 28806901, 2017). "Of particular note, “anti-insulin resistance” therapies, such as insulin, GLP-1 analogs, DPP-4 inhibitors, and APN, may improve insulin receptor signaling by up-regulating the activity of proteases such as IDE and KLK6." (PMID 28649604, 2017). "Also, results of other studies showed an association between early menarcheal age and elevated fasting insulin, insulin resistance (HOMAIR), and A-cell function (HOMA-A), compared with usual menarcheal age." (PMID 27840328, 2017). "This improvement in insulin sensitivity is sustained under palmitate-induced insulin resistance." (PMID 28914811, 2017). "Whether this was the triggering factor for the lower insulin secretion remains unclear, since it was shown that high-fat diets could lead to both, insulin resistance and impaired insulin secretion." (PMID 28443026, 2017). "The secretion of insulin is impaired and/or there is insulin resistance for diabetic patients." (PMID 28490354, 2017). "IRS-1 is activated by insulin via tyrosine phosphorylation of IRS-1 in the normal signaling pathway, but the Ser307 phosphorylation of IRS decreases its ability to phosphorylate tyrosine and can therefore cause insulin resistance." (PMID 28607631, 2017). "This could ultimately result in attenuated ectopic fat accumulation and improved insulin action in insulin sensitive tissues such as skeletal muscle, pancreas and liver, preventing insulin resistance." (PMID 29375478, 2017). "Type 2 diabetic patients suffer from insulin resistance and reduced insulin secretion." (PMID 28107503, 2017). "The increase in insulin levels during OLZ treatment may compensate for the increase in insulin resistance." (PMID 28584269, 2017). "T2DM is a metabolic disease characterized by insulin resistance, which may be joined with reduced insulin production and secretion." (PMID 28914811, 2017). "Thus, in this study, ET was able to correct alterations on metabolic and lipid profile induced by obesity, including, insulin resistance, and increased blood levels of insulin, leptin, and triglycerides." (PMID 29038363, 2017).